MMP2 (matrix metallopeptidase 2)
Diseases named in the same sentence as MMP2 in open-access papers (continued):
Sharing a sentence is not in itself a finding about the gene and the disease.
schizophrenia (9 papers, 2010 to 2025). A major psychotic disorder characterized by abnormalities in the perception or expression of reality. "Nonetheless, there are limited studies of MMP-2 in patients with schizophrenia, particularly in the context of treatment-resistant and chronically medicated patients." (PMID 38429778, 2024). "In particular, MMP-2 modulated the integrity of the BBB and synaptic plasticity, which were posited to underlie certain aspects of schizophrenia pathophysiology." (PMID 38429778, 2024). "Indeed, risperidone and haloperidol were shown to activate MMP-2 and normalize neurogenesis in various animal models of schizophrenia." (PMID 41010622, 2025). "The connection between MMP-2 and inflammatory cytokines suggests a complex interplay that may contribute to the neuropathological changes observed in schizophrenia." (PMID 38429778, 2024). "The aim of this study was to investigate the levels of tumor necrosis factor (TNF) and matrix metalloproteinase-2 (MMP-2) in male patients with treatment-resistant schizophrenia (TRS) and chronic medicated schizophrenia (CMS), and the relationship with psychopathology." (PMID 38429778, 2024). "The relationship between MMP-2 and the severity of clinical symptoms in schizophrenia has not been reported." (PMID 38429778, 2024). "In addition, the schizophrenia-related genes IL10RA and MMP2 showed a trend towards a reduction, to 33% and 45%, respectively, in medial rectus muscles in this data set." (PMID 29302405, 2017). "Therefore, exploring the interaction of TNF-α and MMP-2 in patients with TRS and chronic medicated schizophrenia (CMS) could provide insight into the mechanisms driving treatment resistance and chronicity." (PMID 38429778, 2024).
skin cancer (9 papers, 2006 to 2025). "Overexpression of LM332-γ2 fragments in skin cancer has been associated with several MMPs, including MMP-2, MMP-7, MMP-13, MMP-19, and membrane-type 1 (MT1)-MMP." (PMID 40399946, 2025). "During epithelial–mesenchymal transition (EMT), a key process in cancer progression, MMP-1 and MMP-2 secretion is significantly upregulated, leading to collagen IV fragmentation and destruction of the BM niche in invasive skin cancers." (PMID 40399946, 2025). "According to the results, MMP2 was highly related to cell migration and adhesion, apoptosis, and skin cancer progression." (PMID 36171883, 2022). "In all the patients who developed skin cancer at follow-up, NGAL, MMP-2, and MMP-9 serum levels were dosed again." (PMID 36293148, 2022). "Tsukifuji and colleagues reported an over-expression of MMP-1, MMP-2, and MMP-3 in skin cancer (16 Ak, 6 AK with SCC, and 15 SCC)." (PMID 16893473, 2006). "In addition, O3 induces the activation of collagen degrading metalloproteinases (MMPs) MMP2 and MMP9 that play a role in photoaging and skin cancer progression." (PMID 36009203, 2022).
ulcers (9 papers, 2014 to 2024). "The improvement of ulcer healing was associated with increased expression of MMP-2 and formation of granulation tissue in the peri-ulcer area." (PMID 29095895, 2017). "Furthermore, healed ulcers at 24 weeks are associated with lower levels of evening cortisol, elevated levels of MMP-2 precursor, and increased cortisol awakening." (PMID 38254696, 2024). "Noticeable, inhibition of miR-217 reduces foot ulcer area, improves ulcer healing, and elevates the micro-vessel density through suppressing the levels of inflammatory factors, while up-regulating MMP-2, MMP-9, VEGF, VEGFR-2, and eNOS in DFU rats." (PMID 36875064, 2023). "The acute inflammatory phase of ulcer healing is followed by proliferative phase, in which gelatinases (MMP-2 and MMP-9) are activated to degrade collagens and gelatin for tissue regeneration." (PMID 29095895, 2017). "The improvement in the regeneration process results in the activation of MMP-2 and formation of granulation tissue in ulcer base, thereby leading to reduced ulcer size." (PMID 29095895, 2017). "The statistical analysis showed a positive correlation between MMP-2 expression in the glandular epithelium of UC patients and the presence of erosions or ulcers (p = 0.048, R = 0.377)." (PMID 27034654, 2016). "Moreover, KFX (5,10 mL/kg) increased the prostaglandin E2 (52%) and cyclooxygenase-1 (30%) levels, and improved malondialdehyde (54%), superoxide dismutase (58%), catalase (39%), and nitric oxide (11%) and TNF-α (9%), IL-6 (11%), MMP-9 (54%) and MMP-2 (53%) of ulcer tissue." (PMID 31696757, 2019). "To more specifically evaluate the effects of citral, especially at doses exhibiting a significant reduction in the ulcer base area in HFD-fed animals, we quantified the activity of MMP-2 and -9 (n = 4–5), which are known to mediate ECM degradation, cellular migration, and re-epithelialization." (PMID 36902320, 2023). "A previous study showed that acute and chronic wounds were associated with high levels of MMP-2 and MMP-9, suggesting that non-healing ulcers developed an environment containing high levels of activated MMPs, which results in chronic tissue turnover and failure of wound closure." (PMID 33740985, 2021). "In present study, it is possible to hypothesize that citral acts in collagen availability in the gastric tissue, mainly due to the significant decrease in MMP-9 activity, the non-exacerbated elevation of MMP-2 activity in ulcers, decreasing the ulcer bed area after 10 days of treatment." (PMID 36902320, 2023).
uveal melanoma (9 papers, 2012 to 2024). A melanoma derived from melanocytes of the uveal tract. "In conclusion, our study results suggested that one of the antimetastatic effects of EGCG on uveal melanoma cells was the downregulation of activities of secreted MMP-2 through the inhibition of ERK1/2 phosphorylation." (PMID 25184134, 2014). "The present study revealed that EGCG inhibited the migration and decreased the MMP-2 activity of uveal melanoma cells." (PMID 25184134, 2014). "The involvement of the MAPK pathway in the modulation of MMP-2 activities was demonstrated by treating uveal melanoma cells by ERK inhibitor, which showed that ERK inhibitor could lead to an inhibition of MMP-2 secretion and cell invasion of uveal melanoma cells." (PMID 25184134, 2014). "It has been shown that miR-34a/LGR4 targets MMP2 to mediate EMT, thus regulating migration and invasion of uveal melanoma cells." (PMID 34852712, 2021). "The effects of epigallocatechingallate (EGCG) on the migration and expression of MMP-2 of uveal melanoma cells have not been reported." (PMID 25184134, 2014). "However, the effect of EGCG on the cell migration and MMP-2 secretion in human uveal melanoma cells has not been reported." (PMID 25184134, 2014). "In this context, it is interesting to note that we could not detect PPP-mediated inhibition of MMP-2 expression as previously shown in uveal melanoma cell lines." (PMID 22159423, 2012). "As expected from our previous results with the 2C-ALC cell line MMP-2 activity was not increased in 2C-ALC compared to parental MUM-2C; again, this suggests that ALCAM is necessary, but not sufficient, for an invasive cell phenotype in uveal melanoma." (PMID 22745734, 2012).
acne (8 papers, 2019 to 2026). An inflammatory process of the sebaceous glands which is characterized by comedones, nodules, papules and/or pustules on the skin. "The genotypes and allele frequencies of MMP-2 (-1306C/T) were compared between acne patients and controls." (PMID 31032338, 2019). "There is a significant correlation between the MMP-2 (-1306C/T) polymorphism and the acne vulgaris (P<0.001)." (PMID 31032338, 2019). "In summary, this study suggests that the MMP-2 (-1306C/T) polymorphism in combination with the TIMP-2 (-418G/C) polymorphism are associated with an increased risk of acne in the Chinese Han population." (PMID 31032338, 2019). "This study shows that there was a significant correlation between the MMP-2 (-1306C/T) polymorphism and the acne in the Chinese Han population (P<0.001)." (PMID 31032338, 2019). "Hypertrophic post-acne scarring was associated with the CC genotype of MMP-2." (PMID 35806952, 2022). "However, the effects of these polymorphisms on MMP2 gene activity and the risk of acne should be further explored." (PMID 34133464, 2021). "In this study, a higher percentage of subjects had the MMP-2 CT/TIMP-2 GC genotype in the acne group than in the control group, suggesting that other polymorphisms might interact collectively in MMP-2 and TIMP-2 activity in acne vulgaris." (PMID 31032338, 2019). "Moreover, patients with the MMP-2 CT/TIMP-2 GG genotype were at higher risk of acne, suggesting that MMP-2 gene activity might be downregulated in acne vulgaris." (PMID 31032338, 2019). "A recently published genetic study suggests that the MMP2 (−1306 C/T) polymorphism, in combination with the TIMP2 (−418 G/C) polymorphism, is associated with an increased risk of acne." (PMID 34133464, 2021). "Keratinocytes are an important source of MMPs in acne vulgaris, and P. acnes can induce the expression of several kinds of MMPs, including MMP-2 and MMP-9." (PMID 33082712, 2020). "The effects of MMP-2 (-1306C/T) and TIMP-2 (-418 G/C) polymorphisms on MMP-2 gene activity and the risk of acne vulgaris deserve further investigation." (PMID 31032338, 2019). "This study indicated that the MMP-2 (-1306C/T) polymorphism, in combination with the TIMP-2 (-418G/C) polymorphism, contributes to acne vulgaris susceptibility in the Chinese Han population." (PMID 31032338, 2019). "The aim of this study was to investigate the association of MMP-2 (-1306C/T) and TIMP-2 (-418G/C) polymorphisms with the risk of acne vulgaris in a Chinese Han population." (PMID 31032338, 2019). "Our study is consistent with the results of TIMP-2 (-418G/C) in this report, but we found that patients with the MMP-2 (-1306C/T) polymorphism and with the MMP-2 CT/TIMP-2 GG or GC allele are at higher risk of acne vulgaris." (PMID 31032338, 2019). "Next, we evaluated the relationship between MMP-2 (-1306C/T) genotypes and clinical parameters in acne." (PMID 31032338, 2019). "The observed MMP-2 downregulation (p < 0.05) could contribute to mitigating acne-related scarring, consistent with its established role in collagen remodeling." (PMID 40520168, 2025). "Various MMP1 and MMP2 expression levels may play a role in the formation of different types of acne lesions." (PMID 39347283, 2024). "Among patients with hypertrophic acne scars, 95.8% were shown to have the CC genotype of MMP-2." (PMID 35806952, 2022). "Hypertrophic acne scarring patients with the CC genotype of MMP-2 showed a 7.8-times increased risk of developing hypertrophic acne scars than acne patients without scar formation." (PMID 35806952, 2022). "The aims of this study were to investigate the association of MMP-2 (-1306C/T) and TIMP-2 (-418G/C) polymorphisms with the risk of acne vulgaris in a Chinese Han population and to explore the correlation of clinical phenotype and family history in acne vulgaris patients." (PMID 31032338, 2019).
acne (continued). "Therefore, in order to understand the expression of inflammation in the acne model, we selected the pro-inflammatory cytokine IL-1β, MMP-2, and the anti-inflammatory cytokine IL-10 as the detection indicators in this experiment to observe their expression levels in the acne inflammation model." (PMID 40520168, 2025). "However, few studies have reported correlations of MMP-2 and TIMP-2 polymorphisms with acne." (PMID 31032338, 2019). "The core targets - EGFR, MMP1, MMP2, MMP9, and MMP13 - that directly participate in the relaxin signalling pathway are useful in managing acne by targeting these core targets." (PMID 39347283, 2024). "Specifically, the modulation of EGFR and various MMPs (MMP1, MMP2, MMP9, and MMP13) through the relaxin signalling pathway appears to be a pivotal mechanism by which P. pterocarpum exerts its anti-acne effects." (PMID 39347283, 2024). "Among the 21 common targets of P. pterocarpum and acne, five targets - EGFR, MMP1, MMP2, MMP9, and MMP13 - were selected as the core targets because of their direct involvement in the relaxin signalling pathway." (PMID 39347283, 2024). "Further studies are needed to explore the correlation between MMP-2 activity and expression of IL-1a and β, TNF-α, and triglycerides in acne." (PMID 31032338, 2019). "MMP-2 has been reported to be involved in disrupted integrity of sebaceous glands, and MMP-2 expression significantly decreased after treatment in a mouse model of P. acnes-induced inflammation, suggesting its role in acne." (PMID 31032338, 2019). "Our study suggests that MMP-2 CT/TIMP-2 GG genotype may correspond to decreased activity of MMP-2, which may lead to the high expression of IL-1a and β, TNF-α, and triglycerides observed in acne patients." (PMID 31032338, 2019). "Decreased MMP-2 activity may lead to the production of cytokines such as IL-1β, Pro-IL-1β, TGF-β, latent TNF-α, and elevated triglycerides, which are the key modulators in acne." (PMID 31032338, 2019). "Therefore, a better understanding of the correlation between phenotypes and genotypes of MMP-2 and TIMP-2 in patients with acne may help to further elucidate disease mechanisms." (PMID 31032338, 2019). "MMP-2 is now recognized to cleave a large number of non-matrix substrates, including IGFBPs, IL-1β, pro-IL-1β, latent TGF-β, and latent TNF-α, which are the main factors in acne inflammation." (PMID 31032338, 2019).
adenomyosis (8 papers, 2016 to 2025). The growth of endometrial tissue inside the muscular wall of the uterine corpus. "Compared with the adenomyosis group, the expression of E-cadherin was increased and the expression of N-cadherin, Twist, Snail, MMP-2, and MMP-9 was decreased in mice of verteporfin group." (PMID 36940085, 2023). "We suggest that the increased MT1-MMP expression in adenomyosis observed in our study could be responsible for activation and increased MMP2 expression in adenomyosis." (PMID 37893104, 2023). "Study has demonstrated that berberine has a protective effect on adenomyosis, a complication of PID, by inhibiting the expression of IL-6, IL-8, TGF-β, VEGF and MMP-2." (PMID 30555525, 2018). "In this review, we concentrated on VEGF, EGF, MMP2, IL-6, and TGF-β because we suspect that they may play a major role in the biological processes leading to the establishment and maintenance of adenomyosis." (PMID 26898650, 2016).
aneurysmal disease (8 papers, 2015 to 2025). "In this study, we evaluated the effects of statins on MMP-2, MMP-9, and neutrophil gelatinase-associated lipocalin (NGAL) in both plasma and tissue in patients with aneurysmal disease." (PMID 32111073, 2020). "The current study aims to identify the role of MMP-1, MMP-2, MMP-9, and the MMP inhibitor, TIMP-1, in identifying aortic dilation in children with BAV." (PMID 39408865, 2024). "In this study, we evaluated the expression of MMP-2, MMP-9, and NGAL in the plasma and tissue of patients with aneurysmal diseases." (PMID 32111073, 2020). "In this pilot clinical trial, we evaluated the effects of statins on MMP-2, MMP-9, and NGAL plasma levels in patients with aneurysmal disease." (PMID 32111073, 2020). "First, we measured the immune reactivity of MMP-2, MMP-9, and NGAL in the plasma of patients suffering from aneurysmal disease." (PMID 32111073, 2020). "Hence, the current study proposes to identify whether three MMPs, namely MMP-1, MMP-2, and MMP-9, and the MMP inhibitor, TIMP-1, could be used to predict aortic dilatation in children with BAV." (PMID 39408865, 2024).
disc degeneration (8 papers, 2009 to 2025). "The abnormal expression of MMP2 might cause disc degeneration by accelerating the matrix degradation." (PMID 30915367, 2019). "The activation of AGE-RAGE signaling pathway might cause disc degeneration by accelerating the expression of MMP2." (PMID 30915367, 2019). "Taken together, results from this study suggest that the increased presence of MMP-2 in animal models of disc degeneration may be associated with the degradative changes that are observed in the AF." (PMID 23621950, 2013). "For example, polymorphism in matrix metalloproteinase-2 (MMP-2) and collagen IX genes has been linked to greater disc degeneration, while collagen VI and XI variants have been associated with ossification of the posterior longitudinal ligament (OPLL)." (PMID 41375651, 2025). "The researchers showed that MMPs played a dominant role in IDD and that elevated levels of MMP-2 and MMP-9 were associated with grading of degenerative disc disease." (PMID 35754493, 2022). "As an important member of matrix metalloproteinases (MMPs) family, MMP2 plays a critical role in the excessive breakdown of the extracellular matrix (ECM) during disc degeneration." (PMID 30915367, 2019). "Two established animal models of disc degeneration, static compression and transannular needle puncture of rodent caudal discs, were examined for MMP-2 immunopositivity." (PMID 23621950, 2013). "This suggests that patients prone to disc degeneration have a tendency to have higher transcription of the MMP-2 gene and that among patients with disc degeneration, those with higher transcription of the MMP-2 gene have more severe disease." (PMID 19968600, 2009). "This suggests that MMP-2 may have a functionally significant role in the etiology of degenerative disc disease and could be a potential therapeutic target." (PMID 23621950, 2013). "The results of our study showed an increased expression of MMP-2 and concentration of TIMP-2 in DH compared with its levels in FBSS patients, which can be related to the early phase of process of disc degeneration." (PMID 37799188, 2023).
liver cirrhosis (8 papers, 2011 to 2022). "MMPs more particularly the MMP2 that promote the degradation of ECM in liver cirrhosis should have been secreted by MSC, which in the presence of HGF exhibited increased MMP2 activity, as observed by enhanced fibrolysis and/or prevention of collagen synthesis." (PMID 21526984, 2011). "Pathological overexpression of these inhibitors could reduce MMP-2 proteolytic activity below normal physiological levels, thus causing MMP-2 insufficiency as observed in liver cirrhosis and pancreatitis patients with high TIMP-2 levels." (PMID 30867536, 2019). "Interestingly, our results differ from previous data of the liver cirrhosis rat model which showed increased MMP-2 and MMP-9 activities following FTS treatment." (PMID 21445359, 2011). "MMP-8 levels and activity (along with MMP-2 and MMP-9) have shown to be elevated in alcoholic patients with stage C liver cirrhosis." (PMID 32414178, 2020). "The objective of this study was to determine the roles of transforming growth factor β (TGFβ1), metalloproteinase-2 (MMP2), collagen αI (Collα1) and tissue inhibitor of metalloproteinase-1 (TIMP1) in preventing thioacetamide-induced liver cirrhosis in rats." (PMID 23829630, 2013). "Therefore, promising approaches from this study must focus on TGFβ, Collα1, MMP2, and TIMP1 genes expression to develop new therapy for the treatment of liver cirrhosis." (PMID 23829630, 2013).
primary open-angle glaucoma (8 papers, 2010 to 2025). "Functional gene polymorphisms of these MMPs such as MMP1 −1607 1G/2G (rs1799750), MMP2 −1306 C/T (rs243865), MMP2 −1575 G/A (rs243866), and MMP9 Q279R (rs17576) are thus plausible candidates as risk factors for open angle glaucomas." (PMID 20808730, 2010). "Ussa and co-workers investigated whether the SNPs of the genes encoding MMP1, MMP2, MMP3, MMP9, and MMP17 were related to the response to latanoprost in 124 Spanish patients with open-angle glaucoma." (PMID 39769228, 2024).